PPM1H (protein phosphatase, Mg2+/Mn2+ dependent 1H)
Description:
Dephosphorylates CDKN1B at 'Thr-187', thus removing a signal for proteasomal degradation.
Synonyms: ARHCL1; KIAA1157; URCC2; FLJ13253; NERPP-2C
Tractability: PROTAC: ubiquitination databases record sites on it; its protein half-life has been measured.
Gene: Protein-coding gene on chromosome 12 (62,643,994 to 62,935,163, reverse strand). Ensembl gene ENSG00000111110.
Subcellular location: Nucleus; Cytoplasm
Subcellular location (Human Protein Atlas): Nucleoplasm
Gene Ontology:
Molecular function: identical protein binding; phosphoprotein phosphatase activity; protein binding; protein serine/threonine phosphatase activity
Cellular component: cytoplasm; nucleoplasm; nucleus; glutamatergic synapse; synapse
Genetic constraint (gnomAD): Loss-of-function variants: 22 observed, 38.64 expected, observed/expected ratio (o/e) 0.57, 90% interval 0.41 to 0.81. The upper end of that interval is the gene's LOEUF score, 0.81, which puts it in group 3 of 6, group 1 being the genes least tolerant of losing a copy. Missense variants: 543 observed, 594.97 expected, observed/expected ratio (o/e) 0.91, 90% interval 0.85 to 0.98. Synonymous variants: 281 observed, 245.87 expected, observed/expected ratio (o/e) 1.14, 90% interval 1.04 to 1.26.
Homologues: Orthologues: chimpanzee PPM1H (100% identical), pig PPM1H (97% identical), rabbit PPM1H (97% identical), dog PPM1H (96% identical), mouse Ppm1h (96% identical), rat Ppm1h (96% identical), guinea pig PPM1H (95% identical), tropical clawed frog ppm1h (86% identical), macaque PPM1H (86% identical), zebrafish ppm1h (68% identical), Drosophila melanogaster CG10376 (16% identical), Drosophila melanogaster alph (15% identical), and 7 more. Paralogues in human: PPM1J (54% identical), PPM1M (41% identical), PPM1B (19% identical), PDP2 (18% identical), PPM1A (18% identical), PPM1E (18% identical), PPM1F (18% identical), PPM1N (17% identical), PDP1 (17% identical), PP2D1 (17% identical), PPM1K (16% identical), PPM1L (16% identical), and 4 more.
Diseases named in the same sentence as PPM1H in open-access papers:
PPM1H is named in the same sentence as 21 diseases in open-access papers, as found by Europe PMC text mining. Sharing a sentence is not in itself a finding about the gene and the disease. The quoted sentences say what the papers report.
Parkinson disease (6 papers, 2019 to 2025). A progressive degenerative disorder of the central nervous system characterized by loss of dopamine producing neurons in the substantia nigra and the presence of Lewy bodies in the substantia nigra and locus coeruleus. "PPM1H phosphatase reverses Parkinson's disease-associated, leucine-rich repeat kinase 2 (LRRK2)-mediated, Rab GTPase phosphorylation." (PMID 40912655, 2025). "PPM1H phosphatase reverses Parkinson’s disease-associated, Leucine Rich Repeat Kinase 2-mediated Rab GTPase phosphorylation." (PMID 37889931, 2023). "Understanding how PPM1H modulates LRRK2 activity is of fundamental interest and also important, as activators of PPM1H may eventually benefit Parkinson’s disease patients." (PMID 37889931, 2023). "PPM1H activity enhancers could offer a new therapeutic approach to prevent or treat Parkinson’s disease." (PMID 31663853, 2019). "Targeting this site could represent a strategy to enhance PPM1H-mediated dephosphorylation of LRRK2 substrates, offering a potential therapeutic approach to counteract LRRK2-driven Parkinson’s disease." (PMID 40463289, 2025). "While the functional role of Pppm1h remains uncertain, researchers recently reported that Ppm1h can counteract LRRK2 signaling via Rab protein dephosphorylation, which may potentially link to the molecular mechanisms of LRRK2-mediated neurological disorders such as Parkinson’s disease." (PMID 37806341, 2023).
breast carcinoma (4 papers, 2017 to 2025). "Loss of PPM1H confers trastuzumab resistance by reducing the protein levels of the tumor suppressor p27 in breast cancer." (PMID 40584831, 2025). "The top five genes (NAT1, PPM1H, AREG, ACSS1, CXCL1) with the greatest differences in Z-scores were evaluated in the PIK3CA mutant breast cancer samples from TCGA." (PMID 38802751, 2024). "This suggests that PPM1H and ERBB3 may have some link with HER2 type breast cancer." (PMID 29322925, 2017).
colorectal cancer (4 papers, 2019 to 2025). A primary or metastatic malignant neoplasm that affects the colon or rectum. "Low expression level of PPM1H is associated with worse outcomes in hepatocellular carcinoma, colorectal cancer, and pancreatic cancer." (PMID 40584831, 2025). "Recently, it is reported that PPM1H knockdown in colorectal cancer cells can induce vimentin expression and activate cancer-associated fibroblasts (CAFs), which in turn can promote the proliferation and migration of colorectal cancer cell with low PPM1H expression." (PMID 33125346, 2020). "It has also been suggested that patients whose tumors express low levels of PPM1H have reduced survival from colorectal cancer." (PMID 31663853, 2019).
hepatoma (3 papers, 2023 to 2025). "PPM1H inhibited the proliferation, migration, and invasion of hepatoma cell, and inhibited induced HCC nodule formation." (PMID 40732897, 2025). "Consistently, in PPM1H knockdown cells, co-transfecting ATF6 plasmids barely altered the migration and invasion of Hep-G2 and Huh-7 cells, indicating that ATF6 regulates the proliferation and metastasis of hepatoma cells through the function of PPM1H." (PMID 37456776, 2023). "In our research, we identified the suppressive role of PPM1H in hepatoma cell growth, invasion, and HCC progression." (PMID 37456776, 2023). "The Transwell migration and invasion assays showed that there was little difference between the PPM1H-overexpressing and control groups after PF-4708671 addition, indicating that PPM1H regulates the growth of hepatoma cells through inhibition of RPS6KB1." (PMID 37456776, 2023). "The results of these experiments showed that the phosphorylation level of SMAD1 in hepatoma cells was markedly decreased under the influence of PPM1H." (PMID 37456776, 2023). "We discovered RPS6KB1 as a new PPM1H dephosphorylation substrate, which might play an important role in regulation of hepatoma cell development." (PMID 37456776, 2023). "PPM1H inhibited proliferation, migration, and invasion of hepatoma cells." (PMID 37456776, 2023). "PPM1H suppressed growth, invasion, and tumorigenicity of hepatoma cells." (PMID 37456776, 2023). "In our study, p-RPS6KB1 could be directly dephosphorylated by PPM1H in hepatoma cells." (PMID 37456776, 2023). "Moreover, knockdown of PPM1H enhanced the migration and invasion of hepatoma cells." (PMID 37456776, 2023). "This study found that PPM1H inhibits proliferation, migration, and invasion of hepatoma cells in vitro and suppresses HCC progression in vivo and identified PPM1H as the phosphatase of RPS6KB1 to regulate HCC development." (PMID 37456776, 2023). "Thus, PPM1H might inhibit the migration and invasion of hepatoma cells by affecting the EMT characteristics of cancer cells." (PMID 37456776, 2023). "Moreover, the proliferation, migration, invasion, and tumorigenicity of hepatoma cells and of induced mouse HCC cells were suppressed by PPM1H." (PMID 37456776, 2023). "In the present study, we identified that expression of protein phosphatase magnesium- or manganous-dependent 1H (PPM1H) mRNA and protein can be inhibited by ATF6 in hepatoma cells and mice with liver Atf6 knockdown." (PMID 37456776, 2023). "Interestingly, overexpressing PPM1H still inhibited Transwell migration and invasion of Hep-G2 and Huh-7 cells after blocking phosphorylation of SMAD1 with LDN193189, pointing to the fact that there might be other substrates of PPM1H that regulate hepatoma cell growth and invasion." (PMID 37456776, 2023). "In general, PPM1H, as a downstream gene of ATF6, has a suppressive effect on the growth of hepatoma cells." (PMID 37456776, 2023). "In this study, PPM1H inhibited phosphorylation of SMAD1 and RPS6KB1 in hepatoma cells." (PMID 37456776, 2023).
pancreatic cancer (3 papers, 2019 to 2025). "PPM1H is reported to downregulate in pancreatic cancer cells and the knocking down of PPM1H may induce EMT and the migration of cells." (PMID 36672423, 2023).
prostate carcinoma (2 papers, 2013 to 2020). A carcinoma that arises from epithelial cells of the prostate gland. "However, EPB41L5 and SERINC3 had a high rank based on mutational burden and CNVs, ELOVL6 was annotated as an oncogene in prostate cancer, and PPM1H has been proposed to be an oncogene, due to its relation to PPM1D (a well-studied oncogene in breast, ovarian, and brain cancers)." (PMID 32605588, 2020).
colon adenocarcinoma (1 paper, 2019). "In previous work PPM1H was also reported to be overexpressed in colon adenocarcinoma and co-immunoprecipitated with the CSE1L apoptosis regulator that was suggested to comprise a substrate for PPM1H." (PMID 31663853, 2019).
Salmonella Infections (1 paper, 2025). Infections with bacteria of the genus SALMONELLA. "Further, it would be interesting to determine whether PPM1H is up-regulated in response to Salmonella infection to counteract the protective role of the LRRK2-Rab32-IRG1 complex." (PMID 39874296, 2025).
systemic lupus erythematosus (1 paper, 2020). An autoimmune multi-organ disease typically associated with vasculopathy and autoantibody production. "Intriguingly, a recent study found a genetic association between PPM1H and INFα levels in systemic lupus erythematosus (SLE) patients." (PMID 33105882, 2020).
cancer (5 papers, 2017 to 2023). A tumor composed of atypical neoplastic, often pleomorphic cells that invade other tissues. "PPM1H has been implicated in various intracellular processes that are relevant to cancer, including cell cycle regulation." (PMID 35359359, 2022). "In summary, our study suggests that low PPM1H expression in cancer cells is associated with a poor outcome in CRC (stage I-III) and is a potentially useful IHC marker for the prognosis of CRC." (PMID 30988394, 2019). "The results showed that PPM1H was expressed in cancer and adjacent para-cancer tissues and that the overall staining intensity of PPM1H in tumor tissues is lower than that of adjacent tissues, which is consistent with the trend found in the TCGA data." (PMID 37456776, 2023). "Tumor tissues from 134 HCC patients were analyzed by immunohistochemistry, and PPM1H exhibited higher expression levels in adjacent para-cancer tissues than in HCC tissues." (PMID 37456776, 2023). "The results showed that PPM1H expression in cancer tissues (BRCA [n = 1,085], CHOL [n = 36], and LUAD [n = 483]) was higher than in normal tissues." (PMID 37456776, 2023). "The phosphatase activity of PPM1H inhibits the transduction of signaling pathways involved in cancer progression." (PMID 37456776, 2023). "Three genes (NFE2L3, GTF2IRD1, and PPM1H) were significantly differentially expressed between cancer and normal cells or between cancer and IBDs with greater than 2-fold changes (all P < 0.001)." (PMID 30988394, 2019). "By using small interfering RNA (siRNA) to identify genes involved in trastuzumab resistance, identified several kinases and phosphatases that were upregulated in trastuzumab-resistant cancers, including PPM1H." (PMID 29322925, 2017). "PPM1H knockdown in CRC cells and growth in the corresponding conditional medium increased VIM expression and colon fibroblast proliferation, indicating a transformation of cancer-association fibroblasts (CAFs)." (PMID 30988394, 2019). "Interestingly, when CRC cells were co-cultured with medium from activated CCD18-Co cells, the proliferation and invasiveness of CRC cells were enhanced, indicating that CCD-18Co cells educated by PPM1H-low CRC cells secret some cytokines to promote cancer aggressiveness." (PMID 30988394, 2019). "However, the role of PPM1H may differ depending on the cancer type." (PMID 37456776, 2023).
tumor (4 papers, 2019 to 2025). "Upon multivariate analysis, patients with PPM1H-low tumour had a higher risk of CRC relapse compared with patients with PPM1H-high tumours (HR, 1.370; 95% CI, 1.032 to 1.818; P = 0.029)." (PMID 30988394, 2019). "High PPM1H expression was associated with smaller tumor size." (PMID 37456776, 2023). "In PPM1H-overexpressing xenograft tumor tissues, the expression level of E-cadherin was increased and of N-cadherin was reduced, while knockdown of PPM1H inhibited the expression level of E-cadherin and improved N-cadherin expression." (PMID 37456776, 2023). "PPM1H has been reported to be related to cell proliferation, differentiation, and tumor progression." (PMID 37456776, 2023). "Immunohistochemical analysis of PPM1H expression in liver tissues of HCC patients shows that the PPM1H staining intensity in tumor tissues is somewhat lower than that of adjacent non-tumor tissues, which is consistent with the results of the TCGA analysis." (PMID 37456776, 2023). "In the induced HCC mouse models, there were less tumor nodules in the livers of Ppm1h-mice compared with the control group, and the ratio of liver weight to body weight was also reduced." (PMID 37456776, 2023). "Knockdown of PPM1H obviously enhanced the tumorigenicity and tumor growth of Hep 3B2.1-7 cells, while PPM1H overexpression in Hep 3B2.1-7 cells formed smaller xenogeneic tumors than in the control group." (PMID 37456776, 2023). "PPM1H-overexpressing cells co-infected with ATF6 displayed a little bit larger xenogeneic tumor size than cells co-infected with a control lentivirus; however, the results were statistically not significantly different." (PMID 37456776, 2023). "Patients with PPM1H-low tumours have a lower 5-year disease-free survival rate than patients with PPM1H-high tumours in 2 independent cohorts." (PMID 30988394, 2019). "Based on an IHC examination of the validation data set, we confirmed that patients with tumours that expressed low PPM1H at the protein level still had shorter DFS and DSS." (PMID 30988394, 2019). "Using the NCBI-GEO discovery data set, we found that patients with low PPM1H expression tumours typically had shorter DFS compared with those with high PPM1H expression tumours." (PMID 30988394, 2019). "Next, we began to explore the regulatory relationship between tumour PPM1H expression and mesenchymal VIM expression." (PMID 30988394, 2019). "For stage III CRC, patients with tumours that expressed high PPM1H seemed to benefit more from chemotherapy in the validation data set." (PMID 30988394, 2019). "PPM1H is regarded as a tumor suppressor across various malignancies." (PMID 40584831, 2025). "In addition, PPM1H inhibited induced HCC nodule formation as well as tumor xenograft growth in diethylnitrosamine/CCl4-induced HCC mouse model and nude mouse tumorigenicity assay, respectively." (PMID 37456776, 2023). "To determine whether PPM1H inhibits tumor growth in vivo, we established stable PPM1H- or ATF6-overexpressing and PPM1H knockdown Hep 3B2.1-7 cells." (PMID 37456776, 2023). "After exploring the mechanism by which ENST00000452578 regulates tumor size, we found that ENST00000452578 may regulate the tumor size by regulating PPM1H." (PMID 35359359, 2022). "The preliminary experimental data show that tumour PPM1H may affect EMT of CRC cells and activation of CAFs." (PMID 30988394, 2019). "Because the number of nuclear-staining-positive cells in tumor tissues was higher than that of adjacent tissues, it might hint at the fact that PPM1H expression might be compartmentally increased in nuclei to exert anticancer functions, but this speculation needs to be verified." (PMID 37456776, 2023). "Therefore, our results clearly demonstrate that PPM1H-low tumour cells may activate CAFs and are subsequently supported by CAFs." (PMID 30988394, 2019). "Therefore, our results clearly revealed that low PPM1H expression in CRC could lead to tumour development through activating CAFs." (PMID 30988394, 2019).
tumor (continued). "Lack of tumour PPM1H expression identifies a patient subgroup with a high relapse risk, and CRC cells with low expression of PPM1H activate CAFs and inversely get promoted by CAFs." (PMID 30988394, 2019). "The result showed that the 5-year DFS rate was lower among patients with PPM1H-negative tumours than patients with PPM1H-high tumours (65.9% vs. 75.0%, P = 0.008)." (PMID 30988394, 2019).
PPM1H also shares sentences with these, for which no sentence is quoted: glioma (2 papers); neurological disorders (2); autism (1); brain cancer (1); cholangiocarcinoma (1); endocrine diseases (1); liver cancer (1); lung adenocarcinoma (1); migraine (1); schizophrenia (1).